YAP1 (Yes1 associated transcriptional regulator)
Diseases named in the same sentence as YAP1 in open-access papers (continued):
Sharing a sentence is not in itself a finding about the gene and the disease.
Ataxia (1 paper, 2019). Ataxia refers to impaired coordination of voluntary muscle movement. "The overexpression of Yap1 in neurons restored the thickness of the cerebellar molecular layer and locomotor coordination deficits in a mouse model of ataxia." (PMID 31042703, 2019).
Atrophy (1 paper, 2024). Any weakening or degeneration, especially through lack of use. "The increase in Yap1/Taz/Tead expression and activity, observed shortly after denervation, may represent a physiological response to promote re-innervation and synaptic gene expression, and counteract muscle atrophy caused by denervation induced muscle atrophy." (PMID 38048326, 2024).
Batten disease (1 paper, 2025). "YAP1-mediated pro-apoptotic signaling is also increased as a consequence of CLN3 functional loss in retinal pigment epithelia cells, and in the hippocampus and thalamus of Cln3Δ7/8 mice, an established model of Batten disease." (PMID 41198904, 2025). "Here, we demonstrate in human cell lines and in the brain of a mouse model of Batten disease that loss of CLN3 function causes DNA damage, which triggers a pro-apoptotic response mediated by the transcription factor YAP1, in a c-Abl-dependent and Hippo-independent manner." (PMID 41198904, 2025). "Together, our findings highlight the activation of YAP1 pro-apoptotic signaling via c-Abl activation as a critical pathway in lysosomal dysfunction resulting from impaired GPD efflux, and identify a novel target for possible therapies in Batten disease." (PMID 41198904, 2025).
benign hepatocellular adenoma (1 paper, 2024). "Tumor-specific Notch2 deletion switched the tumor type in the Akt-YAP1 model from cHCC-CCA to a benign hepatocellular adenoma-like tumor at the expense of CCA." (PMID 39273023, 2024).
Blindness (1 paper, 2021). Blindness is the condition of lacking visual perception defined as a profound reduction in visual perception. "The Hippo pathway kinase cascade and its nuclear effectors Yes-Associated-Protein 1 (YAP1) and WW-domain-containing transcription regulator 1 (WWTR1, also known as TAZ) have been associated with ocular disorders that often lead to blindness in mice and humans." (PMID 34616723, 2021).
bone metabolic disorders (1 paper, 2025). "YAP1 deficiency exacerbates ferroptosis and bone loss, providing a novel target for treating bone metabolic disorders." (PMID 41480314, 2025).
bone metastasis (1 paper, 2022). Transfer of a neoplasm from its primary site to bones. "Meanwhile, brain and bone metastasis were less prevalent in patients classified into YAP1 subtype than those with ASCL1 subtype, respectively, and liver metastasis was decreased in YAP1 subtype than NEUROD1 subtype." (PMID 35311069, 2022).
bone tumor (1 paper, 2019). "Overall, moderate to strong nuclear staining of YAP1 and TAZ was detected in 53% (258/486) and 33% (158/486) of soft tissue and bone tumor specimens, respectively." (PMID 31873172, 2019). "Concordance of nuclear YAP1 and TAZ immunoreactivity was demonstrated in a broad range of soft tissue and bone tumor specimens (4–75%)." (PMID 31873172, 2019).
carcinosarcoma (1 paper, 2017). A malignant tumor composed of a mixture of carcinomatous and sarcomatous elements. "Consistent with development of predominantly claudin-low carcinosarcomas in these animals, we found almost all these tumours, except two (E7, E8), exhibited elevated Yap1 expression, which were accompanied by Yap1 gene amplification." (PMID 28194015, 2017).
cardiac ischemia (1 paper, 2025). "We previously showed that lncDach1 impairs cardiac function by promoting the degradation of sarco-endoplasmic reticulum Atp2a2 (SERCA2a), and exacerbates cardiac ischemia injury by inhibiting Yes-associated protein 1 (YAP1) mediated proliferation of neonatal cardiomyocytes." (PMID 39773412, 2025).
central nervous system neuroblastoma (1 paper, 2024). "One study is in Phase 1 (open), and one is in Phase 4 (open), these studies use YAP‐1 expression and central nervous system neuroblastoma as an inclusion criterion." (PMID 38925618, 2024).
cervical tumours (1 paper, 2021). "E6 has been shown to upregulate YAP1 protein levels by shielding it from proteasomal degradation in a manner dependent on its PBM, resulting in the nuclear accumulation of YAP1 in both cervical tumours and HPV-containing keratinocytes." (PMID 33427604, 2021).
childhood cancer (1 paper, 2022). "Future investigations will interrogate the molecular nature of YAP1 and HES1 convergence on CDKN1C, the transcriptional program governed by HES1 in FN‐RMS tumorigenesis, and the impact on FN‐RMS cell fate decisions, informing potential therapeutic opportunities for this childhood cancer." (PMID 36037042, 2022).
chronic asthma (1 paper, 2022). An asthma that is characterized by the development of persistent airway inflammation and recurrent attacks of breathlessness and wheezing, which vary in severity and frequency. "YAP1 is observed to be up-regulated in bronchial airway tissue of a mouse model with chronic asthma and it can enhance the viability and migrative potential of ASM cells." (PMID 35172671, 2022).
chronic cholecystitis (1 paper, 2020). "Interestingly, this pattern was also observed in four chronic cholecystitis patient derived organoids (CC-PDOs), where a high cytoplasmic YAP1 expression was observed in 80%–100% of epithelial cells from PDOs." (PMID 32218280, 2020). "Here, we found that YAP1 and TAZ are highly expressed in over 60% of chronic cholecystitis (CC) and advanced tumors." (PMID 32218280, 2020). "To evaluate the Hippo-YAP1 signaling pathway status in GBC, we performed an exploratory analysis using eight advanced GBC and eight chronic cholecystitis (CC) patient samples." (PMID 32218280, 2020). "Here, we determined the expression levels of the main components of the Hippo-YAP1 signaling pathway YAP1, TAZ and MST1 in GBC and chronic cholecystitis patients." (PMID 32218280, 2020). "In an extended cohort of advanced GBC cases, we showed that expression of YAP1 and MST1 were reduced in GBC compared with chronic cholecystitis." (PMID 32218280, 2020).
chronic heart failure (1 paper, 2020). "The Hippo–YAP1/TAZ pathway, as a mechano-sensor, is affected by mechanical signaling through cell geometry and alterations in cytoskeletal tension; this may help elucidate the pathological mechanism of chronic heart failure." (PMID 32390875, 2020).
cognitive (1 paper, 2025). "In the C57BL/6J mice with YAP1 knockdown, Nr4a1 expression was either knocked down or inhibited with DIM-C to examine the impact of Nr4a1 on tau phosphorylation and cognitive deficits." (PMID 40468463, 2025).
colorectal adenoma (1 paper, 2021). An adenoma that arises from the colon or rectum. "A study has reported that the expression of TEAD4 in colorectal adenomas was positively associated with YAP1 expression and regulated its expression through transcription activation." (PMID 33517828, 2021).
complication (1 paper, 2025). Any disease or disorder that occurs during the course of, or because of, another disease, treatment, or procedure. "This suggests that targeting YAP1 could help control excessive cell growth seen in diabetic vascular complications, pointing to its potential as a therapeutic target." (PMID 41450435, 2025).
congenital heart disease (1 paper, 2020). A heart disease that is present at birth. "For example, a study on congenital heart disease indicated that the low expression of YAP1 induces apoptosis." (PMID 33111745, 2020).
cryptococcosis (1 paper, 2019). An acute or chronic, localized or disseminated infection by Cryptococcus neoformans. "Yap1 has a minor role in the survival of C. neoformans in a murine model of systemic cryptococcosis." (PMID 31748248, 2019). "Here, we further examined the role of Yap1 in C. neoformans virulence using a systemic cryptococcosis murine model." (PMID 31748248, 2019).
depression (1 paper, 2024). "YAP1 was identified as a key molecule contributing to the development of depression and was significantly elevated in depression patients." (PMID 38849737, 2024).
developmental delay (1 paper, 2022). "In an 18-month-old boy with bilateral iris coloboma, staphyloma, morning glory disc anomaly, macular atrophy, microcephaly, hypotonia, dysplastic auricles and developmental delay, we identified the heterozygous frameshift variant NM_001130145.2:c.1196_1199del, p.(Asp399Valfs*3) in the YAP1-gene." (PMID 36553572, 2022).
dry eye (1 paper, 2023). "Several genes of the hippo pathway, including YAP1, TEAD1, or SMAD4, were down-regulated in patients with dry eye." (PMID 38254630, 2023).
Dupuytren disease (1 paper, 2022). "Similarly, elevated YAP1 expression was also found in Dupuytren disease—a condition characterized by the formation of myofibroblast-rich cords and nodules in the hands—where it partly co-localized in αSMA-positive cells." (PMID 35805148, 2022).
Ebola (1 paper, 2021). "The past decade and a half of Hippo/YAP1 research has uncovered countless connections to human diseases ranging from Ebola to oncology and even applications in laboratory-grown meat." (PMID 34685695, 2021).
emphysema (1 paper, 2018). "Yap1,Wwtr1iPCKO double mutant lungs display impaired alveolarization and a severe emphysema-like morphology." (PMID 29934496, 2018).
fallopian tube carcinoma (1 paper, 2024). A carcinoma that arises from epithelial cells of the fallopian tube. "Moreover, HPV oncoproteins drove pelvic metastasis of YAP1-induced fallopian tube carcinoma." (PMID 39271776, 2024).
focal segmental glomerulosclerosis (1 paper, 2021). A renal disorder characterized by sclerotic lesions in the glomeruli. "In a mouse model, podocyte-specific knockout of Yap1 induced proteinuria and focal segmental glomerulosclerosis." (PMID 34545930, 2021).
fungal infection (1 paper, 2009). "Thus, our yap1 overexpression analyses clearly demonstrated that the infection failure in ΔtmpL strains was related to the intracellular accumulation of excess ROS in fungal infection structures." (PMID 19893627, 2009).
gallbladder tumor (1 paper, 2023). "These targets were identified based on the KEGG pathway database and our previous research, which demonstrated that YAP1 promotes gallbladder tumor growth by activating the AXL/MAPK pathway." (PMID 37147639, 2023).
HCMV infection (1 paper, 2025). "HCMV infection reduces TEAD1 activity through four distinct mechanisms: closing of TEAD1-bound chromatin, reduction of YAP1 and phosphorylated YAP1 levels, reduction of TEAD1 transcript and protein levels, and alteration of TEAD1 exon 6 usage." (PMID 40928347, 2025). "A previous report has shown that HCMV infection inhibits the proliferation and invasion of extravillous cytotrophoblasts (EVT) through mRNA downregulation of core Hippo pathway components, including downregulation of YAP1/TAZ and all four TEAD TFs." (PMID 40928347, 2025). "The YAP1–TEAD complex exerts its activity by binding to enhancers of genes involved in extracellular matrix organization, actin cytoskeleton organization, and cell adhesion, all of which are pathways for which we see significantly altered gene expression levels subsequent to HCMV infection." (PMID 40928347, 2025).
hydatidiform mole (1 paper, 2023). A gestational trophoblastic disorder characterized by marked enlargement of the chorionic villi, hyperplasia of the villous trophoblastic cells and hydropic changes. "In addition, in hydatidiform moles, PADI6 can regulate trophoblast cell migration-invasion through Hippo/YAP1 Pathway." (PMID 37712067, 2023).
Hypercholesterolemia (1 paper, 2017). An increased concentration of cholesterol in the blood. "Moreover, fluvastatin, which has been generally used to treat hypercholesterolemia and recently has also been shown to module YAP1/TAZ activity, effectively decreased cell migration and invasion in these MPM cell lines." (PMID 29212185, 2017).
Hyperkalemia (1 paper, 2022). An abnormally increased potassium concentration in the blood. "Importantly, this model identified YAP1-driven TC polyploidy as a survival mechanism protecting from hyperkalemia and uremic death." (PMID 36195583, 2022).
hypertensive heart disease (1 paper, 2022). Abnormal enlargement of the heart resulting from long-standing hypertension. "Thus, this study not only provided proof-of-concept evidence that YAP1 was an effective therapeutic target, but also pointed out a compound that could be repurposed to treat hypertensive heart diseases." (PMID 36276651, 2022).
Infertility (1 paper, 2026). "This work identifies Hippo signaling as an unrecognized regulatory layer in luteal steroidogenesis and highlights YAP1/TAZ as potential therapeutic target for luteal insufficiency and infertility." (PMID 42067828, 2026).
insulinoma (1 paper, 2016). "Through immunofluorescence, we detected the expression of Yap1 protein in rodent insulinoma cell lines, such as INS-1 832/13 and MIN6." (PMID 27000077, 2016). "Weak expression of Yap1 was detected in these insulinoma cell lines." (PMID 27000077, 2016). "In this study, we explored the role of Yap1 in rodent insulinoma cell lines." (PMID 27000077, 2016). "Our loss- and gain-of-function analyses using rodent insulinoma cell lines revealed that Yap1 suppresses palmitate-induced apoptosis in β-cells without regulating their proliferation." (PMID 27000077, 2016).
intestinal cancer (1 paper, 2022).
ischemia (1 paper, 2025). A hypoperfusion of the BLOOD through an organ or tissue caused by a PATHOLOGIC CONSTRICTION or obstruction of its BLOOD VESSELS, or an absence of BLOOD CIRCULATION. "However, when tissue stress caused by ischemia persists or the repair process fails, YAP1 translocates to the nucleus and binds to the transcription factor TEAD, inducing the expression of pro-fibrotic factors." (PMID 41380965, 2025).
Kyphoscoliosis (1 paper, 2026). An abnormal curvature of the spine in both a coronal (lateral) and sagittal (back-to-front) plane. "Thereafter, frank kyphoscoliosis accompanied by additional vertebral defects developed in around a third of the surviving yap1 mutants and was first detected at 11 dpf." (PMID 42207799, 2026). "Although the cell type/s of cell autonomous yap1 action remain unclear, we hypothesise that Yap1 mechanosensation mediates feedback between bone, muscle and tendon to restrain vertebral overgrowth and protect against the development of kyphoscoliosis." (PMID 42207799, 2026).
leprosy (1 paper, 2018). Leprosy is a chronic infectious disease affecting primarily the skin and peripheral nervous system.
lipodystrophy (1 paper, 2024). A congenital or acquired disorder characterized by abnormal loss or redistribution of the adipose tissue in the body. "While lipodystrophy observed in BaKO was prevented in BYTaKO, single Yap1 or Taz deletion was insufficient to restore the BaKO phenotypes." (PMID 38744820, 2024).
liver failure (1 paper, 2019). A liver disease characterized by the liver losing or has lost all of its function. "Given that transient arrest at the M‐phase is the most defining cell cycle defect in resection‐induced liver failure, nuclear YAP1 cannot be associated with the regulation of the M‐phase in these settings." (PMID 30740593, 2019). "Such a role is reflected in resection‐induced liver failure with deficient S‐ and M‐phase progression, where YAP1 fails to be induced during the S‐phase peak, but is upregulated during the M‐phase." (PMID 30740593, 2019). "When assessing a model of resection‐induced liver failure (extended 86%‐hepatectomy, eHx) featuring deficient S‐ and M‐phase progression, YAP1 was not induced at 32 hours, but upregulated at 48 hours post‐eHx, confirming its dissociation from M‐phase regulation." (PMID 30740593, 2019).
liver inflammation (1 paper, 2024). "For example, in the Kupffer cells, activation of YAP1 enhanced the production of proinflammatory cytokines and promoted the development of liver inflammation." (PMID 38540020, 2024).
lysosomal storage disorder (1 paper, 2022). "For example, cardiac-specific knockout of the genes encoding the lysosomal proteins Rag family protein A/B (RagA/B) causes lysosomal storage disorder characterized by increased autophagosome accumulation due to the activation of yes-associated protein 1 (YAP1)-TFEB transcription." (PMID 36312227, 2022).
mediastinal tumors (1 paper, 2023). "Recently, two additional patients with mediastinal tumors with YAP1::MAML2 rearrangements were reported that followed a more aggressive clinical course." (PMID 38067300, 2023).
memory impairment (1 paper, 2025). "Moreover, MWM test demonstrated that YAP1 overexpression effectively ameliorated learning and memory impairments in SAMP8 mice." (PMID 40468463, 2025).
meningitis (1 paper, 2019). A disorder characterized by acute inflammation of the meninges of the brain and/or spinal cord. "The human meningitis fungal pathogen, Cryptococcus neoformans, contains the atypical yeast AP-1-like protein Yap1." (PMID 31748248, 2019). "IMPORTANCE The human meningitis fungal pathogen, Cryptococcus neoformans, contains the atypical yeast AP-1-like protein Yap1." (PMID 31748248, 2019).
mesenchymal neoplasms (1 paper, 2025). "Recurrent KMT2A and YAP1 related fusions have recently been reported in various mesenchymal neoplasms of different histogenesis." (PMID 40879254, 2025).
metastatic melanoma (1 paper, 2024). A melanoma that has spread from its primary site to another anatomic site. "In metastatic melanoma cells, YAP1/TAZ activity could be increased by reducing Ca2+ influx." (PMID 38540020, 2024).
muscular atrophy (1 paper, 2019). The loss of muscle tissue due to inactivity or disease. "Our findings suggest that cyclic vibration stimuli (90 Hz, 15 min, once a day) are useful to induce the expression of YAP1, leading to the recovery of muscular atrophy." (PMID 31281262, 2019). "Collectively, our results indicate that cyclic vibration stimuli can effectively activate satellite cells and facilitate recovery from immobilization-induced skeletal muscle atrophy through the upregulation of MGF and YAP1 expression." (PMID 31281262, 2019).
muscular dystrophy (1 paper, 2018). Muscular dystrophy (MD) refers to a group of more than 30 genetic diseases characterized by progressive weakness and degeneration of the skeletal muscles that control movement. "We demonstrated for the first time that YAP1 expression is decreased and LATS1/2 kinase activity increased in DMD muscles but not in muscles from patients with other types of muscular dystrophy, stressing the specificity of the results." (PMID 30304034, 2018).
myelofibrosis (1 paper, 2024). A partial or complete replacement of the bone marrow stroma by fibrous tissue. "Furthermore, the identification of vascular defects in the ThPO and MPL models of myelofibrosis raises the possibility that EndMT, increased biological activity of YAP1/TAZ and SRF-mediated changes in gene expression, but also EC cytoskeletal function, might contribute to fibrosis." (PMID 39155965, 2024).